PPARG (peroxisome proliferator activated receptor gamma)
Diseases named in the same sentence as PPARG in open-access papers (continued):
Sharing a sentence is not in itself a finding about the gene and the disease.
myocardial infarction (72 papers, 2008 to 2026). Gross necrosis of the myocardium, as a result of interruption of the blood supply to the area, as in coronary thrombosis. "Given the known cardiovascular risks associated with high-dose rosiglitazone, such as myocardial infarction, it is crucial to balance these potential adverse effects with the therapeutic benefits of PPARγ activation." (PMID 40295383, 2025). "Thiazolidinediones, as ligands for PPARG, have been shown to reduce tissue necrosis associated with acute myocardial infarction." (PMID 40510478, 2025). "Studies indicate that Sirtuin 3 activator theacrine improved heart function after estrogen-deficient mice myocardial infarction by boosting sirtuin 3 levels and modulating the β-catenin/PPARγ signaling pathway." (PMID 39256355, 2024). "The PPARG Pro12Ala allele was associated with a reduced risk of myocardial infarction in a Type 2 diabetic population, while the T allele of the C1431T polymorphism was associated with increased all-cause mortality." (PMID 36768666, 2023). "They found an association between the PPARG Pro12Ala variant and decreased risk of myocardial infarction, while the C1431T genotype had the opposite effect." (PMID 33322384, 2020). "Our results shed light on the understanding of the PPARG-MI association, suggesting PPARG as a potential therapeutic target for the treatment of myocardial infarction." (PMID 32565767, 2020). "Studies have demonstrated that several chemically distinct agonists of PPARγ reduce myocardial infarct size caused by regional I/R in rats." (PMID 28744220, 2017). "Some studies found that chronic activation of PPARα is detrimental to cardiac recovery after ischemia and PPARγ activator was associated with increased mortality post-myocardial infarction in rats." (PMID 27955667, 2016). "In the case of T2D, nutraceuticals have the potential to decrease the risk of myocardial infarction, weight gain, and edema associated with current synthetic PPARγ agonist treatments." (PMID 19746174, 2010). "A recent report claimed that miR‐130 could exacerbate myocardial injury caused by acute myocardial infarction by targeting PPARγ." (PMID 34989130, 2022). "A specific PPARγ agonist has been withdrawn from the market, as rosiglitazone was associated with a significant increase in the risk of death from cardiovascular causes, from myocardial infarction." (PMID 30424016, 2018). "The PPARγ agonist Rosiglitazone was withdrawn due to increased risk of myocardial infarction." (PMID 30486822, 2018). "The PPARG A12 allele was also associated with a reduced risk of myocardial infarction." (PMID 26949382, 2016). "In conclusion, although PPARγ agonists offer benefits in the treatment of diabetes and atherosclerosis, known risk factors associated with cardiovascular disease, they also have deleterious effects such as increased risk incidence of myocardial infarction and heart failure." (PMID 33322384, 2020). "However, there are conflicting reports demonstrating that administration of PPARγ agonists may be associated with an increased incidence of congestive heart failure, myocardial infarct and death." (PMID 20040043, 2010). "Myocardial cells at the periphery of myocardial infarction showed decreased expression of sirtuin 3 and peroxisome proliferator-activated receptor γ (PPARγ), but dramatically enhanced expression of β-catenin." (PMID 39256355, 2024). "First, elevated levels of FGF21 in ischemic heart injury, including myocardial infarction, inhibit the phosphorylation of PPARγ, which is the active form of PPARγ, thus suppressing adipose browning in WAT." (PMID 37667400, 2023). "Curcumin also inhibited myocardial cell necrosis and apoptosis by abrogating NF-κB expression and stimulating expression of PPARγ and B-cell lymphoma 2 (Bcl-2) in myocardial cells in a rat myocardial infarction model." (PMID 36092543, 2022).
myocardial infarction (continued). "Pioglitazone, a PPARγ agonist, enhanced the therapeutic effects of adipose tissue-derived regenerative cells on chronic myocardial infarction by stimulating adiponectin paracrine activity and M2 macrophage polarization." (PMID 36114541, 2022). "miR-711 was upregulated by PPARγ post myocardial infarction and promoted endoplasmic reticulum stress-induced cardiomyocyte apoptosis by targeting calnexin." (PMID 36114541, 2022). "QLQX has been reported to improve cardiac energy metabolism and prevent cardiac remodeling in myocardial infarction mice via activating PPARγ." (PMID 34336956, 2021). "Beta-sitosterol can reduce the area of myocardial infarction and cardiac cell apoptosis by modulating PPARγ/NF-κB signals to delay myocardial damage." (PMID 34868332, 2021). "Our previous studies have demonstrated that QLQX has a beneficial effect on heart failure patients and can attenuate cardiac remodeling via activating PPARγ in post-myocardial infarction mice." (PMID 34336956, 2021). "PPARG can adjust the balance between glucose and fatty acid oxidation, which plays an important role in the reconstruction of human myocardial infarction after ischemia." (PMID 34239024, 2021). "The importance of PPARγ expression in myeloid cells for cardiac repair after infarction has been supported by the group of Duan, which analyzed the outcomes of myocardial infarctions in mice with myeloid specific knockout for PPARγ." (PMID 33322384, 2020). "In this study, literature-based Elsevier Pathway Studio information and expression data retrieved from Gene Expression Omnibus (GEO) were integrated to explore the specific molecules and pathways connecting PPARG and myocardial infarction." (PMID 32565767, 2020). "MiR-130 increases acute myocardial infarction (AMI)-induced heart injury by inhibiting peroxisome proliferator-activated receptor gamma (PPAR-γ)." (PMID 33681183, 2020). "All of this evidence indicates that PPARG not only works in the progression of myocardial infarction but also plays a role in the functional recovery and cellular protection of myocardial infarction." (PMID 32565767, 2020). "PPARγ has been shown to benefit cardiovascular disease therapies, such as those pertaining to ventricular hypertrophy, cardiac remodeling and acute myocardial infarction." (PMID 30419807, 2018). "Pigment epithelial-derived factor and its functional peptides inhibit angiogenesis by means of upregulation of PPARγ in a rat model of acute myocardial infarction and in an in vitro model of myocardial angiogenesis." (PMID 29312293, 2017). "Altogether, this data suggests that the reduction in myocardial infarct size afforded by these drugs is, at least in part, due to their ability to activate PPARγ." (PMID 28744220, 2017). "For example, treatment with telmisartan and PIO, PPARγ agonists, can substantially reduce I/R-induced myocardial infarct size." (PMID 28744220, 2017). "The PPARγ Pro12Ala polymorphism is associated with a reduced risk of myocardial infarction (MI) according to the Physician's Health Study but confers an increased risk of MI or cardiac death according to the Health Professionals Follow-Up Study." (PMID 28042289, 2016). "The role and underlying mechanisms of rosiglitazone, a peroxisome proliferator-activated receptor-gamma (PPAR-γ) agonist, on myocardial infarction are poorly understood." (PMID 22140576, 2011). "PPARγ is present in monocytes/macrophages, neutrophils, and platelets, which suggests a role for PPARγ in negatively regulating expression ofproinflammatory genes and thus, myocardial infarction." (PMID 18288284, 2008). "Interestingly, the knockout of PPARγ in myeloid cells worsened the outcome after experimental myocardial infarction in mice, likely due to increased oxidative stress and cardiac inflammation." (PMID 36768666, 2023). "Moreover, knockdown of miR-130 boosts PPARG activation and mitigates myocardial injury resulting from myocardial infarction." (PMID 35599576, 2022).
myocardial infarction (continued). "Furthermore, SIRT3 inhibited myocardial fibrosis and apoptosis after myocardial infarction by regulating the ß-catenin/PPARγ signal pathway." (PMID 34422410, 2021). "Moreover, theacrine (alkaloid derived from Chinese tea) inhibited myocardial infarction-evoked fibrosis via stimulation of PPARG and SIRT3 expression." (PMID 34830207, 2021). "This study confirmed the downregulation of PPARG in the case of myocardial infarction and revealed multiple pathways through which PPARG could regulate the development of myocardial infarction." (PMID 32565767, 2020). "Later meta-analyses did not support a role of P12A polymorphism in the PPARγ gene in myocardial infarction or coronary heart disease risk." (PMID 33322384, 2020). "Both the metabolic-and nutrient-associated pathways involved in the development and progress of myocardial infarction can be regulated by PPARG, which indicates that PPARG might be utilized as an essential target in myocardial infarction treatment." (PMID 32565767, 2020). "Peroxisome proliferator-activated receptor γ (PPARG) might play a protective role in the development of myocardial infarction (MI) with limited mechanisms identified." (PMID 32565767, 2020). "Although some simulators of PPARG have been testified to show a protective effect on the development of myocardial infarction, a systemic literature text mining investigation has been performed to screen the genes and relevant molecular pathways connecting PPARG to myocardial infarction." (PMID 32565767, 2020). "Shinmura and colleagues used the PPARγ agonist pioglitazone to enhance the cardiomyogenic transdifferentiation potential of human marrow-derived mesenchymal stem cells (MSCs), which they injected two weeks after myocardial infarction in nude rats." (PMID 33322384, 2020). "Literature-based knowledge database and expression data integration may significantly promote the illustration of the relevant mechanism involved in PPARG-mediated myocardial infarction protection." (PMID 32565767, 2020). "Ligands of PPARγ and PPARα have been demonstrated to reduce myocardial infarct size in I/R; therefore, PPAR agonists may be useful in conditions associated with I/R injury of the heart and other organs." (PMID 30800167, 2019). "Correspondingly, modulating the PPAR pathway was recognized as an attractive therapeutic avenue for treating cardiac remodeling and Pioglitazone, a PPARγ agonist, was shown to attenuate cardiac remodeling and heart failure after experimental myocardial infarction (MI)." (PMID 24667808, 2014). "Progressive down-regulation of peroxisome proliferator-activated receptor γ (PPARγ) has been reported in patients with acute myocardial infarction undergoing coronary artery bypass grafting and in the mouse model of MI/RI." (PMID 38347951, 2024). "Through PPARγ activation, TFPI2 fosters M2 polarization and mitigates vascular injury following myocardial infarction." (PMID 40361374, 2025). "As the nuclear hormone receptor superfamily of ligand-activated transcription factors, PPARG could recruit transcription coactivators that are necessary for the initiation of target gene transcription and may also inhibit the development and progress of myocardial infarction." (PMID 32565767, 2020). "Interestingly, the regulation of PPARγ by pioglitazone suppressed cardiac hypertrophy as indicated by decreased heart/body weight ratio, wall thickness, and myocyte diameter, but the effect of pioglitazone on limiting myocardial infarct size was a PPARγ-independent event." (PMID 32028670, 2020). "Furthermore, when hypercholesterolemic rabbits were pretreated with the PPARG agonist rosiglitazone prior to ischemia/reperfusion or AMI, there was a significant decrease in the number of apoptotic cardiomyocytes and size of myocardial infarct observed." (PMID 31850068, 2019).
myocardial infarction (continued). "Expression levels of PPARγ were found to be up-regulated after myocardial infarction in rats, however, increased PPARγ could not counteract the decrease in metabolic genes." (PMID 33322384, 2020). "We hypothesized that combined administration of PPARγ agonists and ADRCs may enhance the paracrine effects of adiponectin (APN), leading to functional recovery in a chronic myocardial infarction (MI) model." (PMID 30902059, 2019).
osteoporosis (72 papers, 2006 to 2026). A condition of reduced bone mass, with decreased cortical thickness and a decrease in the number and size of the trabeculae of cancellous bone (but normal chemical composition), resulting in increased fracture incidence. "For example, PPARG is a biomarker for osteoporosis, and the PPAR-γ protein it encodes is a key regulator of adipocyte differentiation." (PMID 40299567, 2025). "This in addition to the fact that PPARγ promotes sclerostin (SOST) production which is considered one of the best targets for osteoporosis and the fact that PPARγ is associated with the regulation of ROS, makes it a lucrative target for osteoporosis as well." (PMID 39707534, 2024). "Due to the possible influence of the ECE1 gene on bone mineral density and the PPARG gene on the maintenance of bone mass, we selected several variants of these to assess their influence on the development of osteoporosis." (PMID 39062013, 2024). "In our study, we analyzed the influence of the ECE1 rs213045 and rs213046 variants and the PPARG rs1801282 variant on the occurrence of osteopenia and osteoporosis in postmenopausal women." (PMID 39062013, 2024). "The association between increased adipose cells and osteoporosis can be attributed to the inhibitory effect of PPARγ on bone formation." (PMID 37513946, 2023). "Another well-known side-effect of synthetic PPARγ agonists is the impairment of osteoblastogenesis leading to osteoporosis and increased fracture risk." (PMID 24265809, 2013). "The reciprocal relationship between PPARγ levels andosteogenesis is particularly evident with increased age, supporting a role for PPARγ in bonedevelopment and osteoporosis associated with aging." (PMID 17259665, 2006). "Therefore, we analyzed the association of the ECE1 and PPARG variants with osteopenia and osteoporosis risk in the Polish population." (PMID 39062013, 2024). "In addition, in obese populations, PPARγ can inhibit osteoblast differentiation through Runx2 reduction, leading to bone loss and osteoporosis." (PMID 38475712, 2024). "However, PPARγ agonists have been found in clinical trials to increase the risk of water-sodium retention, osteoporosis, adipocyte hyperplasia, and myocardial hypertrophy, which greatly limits their applications in patients with cardiovascular disease." (PMID 36518993, 2022). "As a key regulator of glucose and lipid metabolismas gene PPARγ should be focused on for its close links with the occurrence of osteoporosis, which may also be the possible mechanism underlying TFDR-mediated GIOP treatment." (PMID 35846330, 2022). "PPARγ is a transcription factor that has been implicated in the development of osteoporosis." (PMID 22518296, 2012). "Additionally, PPARγ was identified as a key metabolic regulator associated with osteoporosis." (PMID 41562931, 2026). "Moreover, another study suggested that the PPARG rs12497191, rs1801282, and rs3856806 variants may be associated with osteoporosis, especially the common rs1801282 variant." (PMID 39062013, 2024). "Collectively, these findings establish NF-κB p65 and PPARγ as experimentally validated hub targets of asiatic acid in osteoporosis, whereas direct modulation of IL-6 and STAT3 has remained insufficiently characterized." (PMID 41562931, 2026). "Metabolic regulators such as peroxisome proliferator-activated receptor γ (PPARγ) also contribute to osteoporosis by shifting mesenchymal stem cell differentiation toward adipogenesis at the expense of osteoblastogenesis, thereby impairing bone formation." (PMID 41562931, 2026). "Synthetic PPARγ agonists thiazolidinediones are anti-diabetic drugs with adverse effects, including weight gain, fluid retention, and osteoporosis." (PMID 40119175, 2025). "Discussing the competitive mechanisms of adipogenesis and osteogenesis, the adipogenic differentiation of mesenchymal stromal cells is notably enhanced during disuse osteoporosis, particularly with the increase in PPARG expression." (PMID 40130165, 2025).